HK1 (hexokinase 1)
Diseases named in the same sentence as HK1 in open-access papers (continued):
Sharing a sentence is not in itself a finding about the gene and the disease.
heart failure (5 papers, 2014 to 2023). Inability of the heart to pump blood at an adequate rate to meet tissue metabolic requirements. "hK1-specific amidase activity is reduced in urine samples from hypertensiveand heart failure (HF) patients." (PMID 26351984, 2015). "Therefore, it is essential to continue to explore the role of HK1 in altered energy metabolism in heart failure, which will provide potential therapeutic strategies for the treatment of HF." (PMID 37938421, 2023). "Therefore, promoting the binding of HK1 to mitochondria is a new therapeutic direction to improve heart failure." (PMID 37938421, 2023). "However, Drake JI and colleagues screened and compared different gene expressions between right ventricle hypertrophy and heart failure using gene chip technology, they found HK1 and PFK gene expression was increased in the failing RV compared with the hypertrophied RV." (PMID 25287584, 2014).
liver fibrosis (5 papers, 2022 to 2025). "In the TME of hepatic fibrosis, hexokinase 1 (HK1) secreted from HSCs via large EVs can be captured by HCC cells and can promote tumor glycolysis and progression." (PMID 39227992, 2024). "The effects of PDNPA on elevating Nur77 expression and suppressing HK1 secretion were also demonstrated in TGF-β-treated primary HSCs or primary HSCs derived from the CCl4-induced liver fibrosis model (left)." (PMID 36192599, 2022). "During TGF-β-induced liver fibrosis, the palmitoylation of HK1 was enhanced in activated HSCs, leading to lEV HK1 secretion." (PMID 36192599, 2022). "Although the HK1 expression levels in mouse primary HSCs from control mice and mice with CCl4-induced hepatic fibrosis were almost the same in whole cell lysates, the secretion of HK1 via lEVs was enhanced in CCl4-treated mice (left)." (PMID 36192599, 2022). "Anti-hexokinase 1 (HK1) antibodies revealed a specific association with a higher likelihood of LREs and lower transplant-free survival, while anti-Kelch-like 12 (KLHL12) antibodies showed a link to advanced liver fibrosis and elevated bilirubin levels." (PMID 41440960, 2025). "Given that TGF-β was found to trigger lEV HK1 secretion in HSCs and that Nur77 expression was suppressed during liver fibrosis, we hypothesized that Nur77 is involved in the regulation of HK1 secretion in HSCs." (PMID 36192599, 2022). "Collectively, liver fibrosis is accompanied by the secretion of HK1 via lEVs." (PMID 36192599, 2022). "Since the expression of ABHD17B was suppressed by TGF-β, we concluded that during liver fibrosis, TGF-β facilitates HK1 secretion by inhibiting ABHD17B-dependent depalmitoylation of HK1." (PMID 36192599, 2022). "Here we demonstrate that in hepatic fibrosis, TGF-β stimulates the palmitoylation of hexokinase 1 (HK1) in hepatic stellate cells (HSCs), which facilitates the secretion of HK1 via large extracellular vesicles in a TSG101-dependent manner." (PMID 36192599, 2022). "Similarly, knockout of HK1 in HSCs did not influence hepatic fibrosis in mice of the CCl4-induced liver fibrosis model." (PMID 36192599, 2022).
anemia (4 papers, 2019 to 2022). A reduction in the number of red blood cells, the amount of hemoglobin, and/or the volume of packed red blood cells. "Mutations in HK1 have been implicated in anemia, together with severe hemolysis and marked decreases in red blood cells." (PMID 36574455, 2022). "Disruption of Hk1 leads to complete infertility in homozygous females, but also has broader deleterious effects on both sexes due to severe anemia which may hinder efficient gene drive spread via males." (PMID 34025776, 2021).
esophageal cancer (4 papers, 2016 to 2025). A primary or metastatic malignant neoplasm involving the esophagus. "Artesunate can promote the degradation of hexokinase 1 (HK1) by targeting it, while simultaneously downregulating the levels of HIF1α and PKM2, thereby inhibiting aerobic glycolysis in esophageal cancer progression." (PMID 40758729, 2025).
Hypoglycemia (4 papers, 2019 to 2025). A decreased concentration of glucose in the blood. "Ectopic Hk1 expression in β cells accelerates glycolysis in low glucose and causes basal insulin hypersecretion and hypoglycemia similar to that in Lsd1Δβ mice 3 weeks after Lsd1 inactivation." (PMID 36821378, 2023). "Therefore, HK1 may be favored in gray matter as the lower Km allows for greater enzymatic activity at typical blood glucose concentrations, and especially under conditions of hypoglycemia." (PMID 39314314, 2024).
liver cancer (4 papers, 2018 to 2024). An epithelial or non-epithelial malignant neoplasm that arises from the liver. "Moreover, analysis of HK1 and HK2 expression in the TCGA liver cancer dataset demonstrates that a substantial portion (83%) of HK2+ (HK2 RSEM > 1000) liver cancers are deficient in HK1 expression (HK1 RSEM < 1000)." (PMID 29988332, 2018). "To examine tumor cell growth inhibition in response to HK2 knockdown, we investigated the consequences of expressing an HK2-targeted doxycycline (DOX)-inducible shRNA in our panel of HK1−HK2+ and HK1+HK2+ liver cancer cell lines." (PMID 29988332, 2018). "While the majority of cancers including liver cancer, from many tissues of origin, express both HK1 and HK2, in many types of cancers, there exist subsets of HK1−HK2+ tumors, i.e., tumors that express only HK2." (PMID 29988332, 2018). "In liver cancer cell lines such as Hep3B, HepG2, JHH5, JHH7, and Huh7, the expression of HK2 has been observed, while in other cancers such as lung, breast, colon, and also in HLF and HH6, liver cancer cell lines are expressed as both HK2 and HK1." (PMID 33809480, 2021). "To confirm and extend these observations, we evaluated the expression of HK1 and HK2 in human liver samples and in a collection of liver cancer cell lines." (PMID 29988332, 2018). "Moreover, as expected from the TCGA data, these liver cancer cell lines fall into two subpopulations: HK1−HK2+ (Hep3B, HepG2, JHH5, JHH7, Huh7) and HK1+HK2+ (HLF, JHH6)." (PMID 29988332, 2018). "However, the synergism/synthetic lethality between HK2 knockdown and DPI is restricted to HK1−HK2+ cancer cells and is not observed in HK1+HK2+ liver cancer cells or in HK1+HK2+ cancer cells from other tissues." (PMID 29988332, 2018). "We find neither cell proliferation nor colony formation are affected by shHK2DOX HK2 inhibition for HK1+HK2+ HLF and JHH6 liver cancer cells, suggesting pharmacologic HK2 inhibition will not have therapeutic efficacy for HK1+HK2+ liver cancers." (PMID 29988332, 2018).
osteoarthritis (4 papers, 2019 to 2025). A noninflammatory degenerative joint disease occurring chiefly in older persons, characterized by degeneration of the articular cartilage, hypertrophy of bone at the margins and changes in the synovial membrane. "Both HK1 and HK2 serve as the first rate-limiting enzyme in glycolysis, implicating their involvement in metabolic derangements in osteoarthritis chondrocytes." (PMID 37134114, 2023).
retinoblastoma (4 papers, 2022 to 2025). A malignant tumor that originates in the nuclear layer of the retina. "The present study identifies RB1 and HK1 as previously unrecognized regulators of metabolic adaptation in retinoblastoma cells." (PMID 36291051, 2022). "In studies, we have identified low expression of the glycolytic HK1 protein and pyruvate in Rb tumors, and we further revealed that ectopic expression of RB1 induces HK1 in Rb null retinoblastoma cells." (PMID 36291051, 2022). "Rescuing RB1 or HK1 in retinoblastoma cells shifted the cellular metabolic profile to glycolysis dependence, consequently reducing mitochondrial ATP production." (PMID 36291051, 2022). "Conversely, the data show a significant reduction in mitochondrial function and mass in Rb- and HK1-complemented retinoblastoma cells characterized by a metabolic switch from OXPHOS to glycolysis and reduced fuel utilization flexibility." (PMID 36291051, 2022). "We found that retinoblastoma tumors and in-vitro models lack Hexokinase 1 (HK1) and exhibit elevated fatty acid oxidation." (PMID 36291051, 2022). "In conclusion, we demonstrate Hexokinase 1 (HK1) to be significantly reduced in Rb tumors and RB1 null retinoblastoma cells, wherein their loss mediates a critical metabolic adaptation towards enhanced mitochondrial respiration." (PMID 36291051, 2022). "To elucidate how RB1 influences HK1 and E2F2 expression in the context of cancer, we overexpressed the wild-type RB1 in Rb null WERI-Rb1 retinoblastoma cells in vitro." (PMID 35626705, 2022). "HK1 levels are significantly low in retinoblastoma tumors and RB1-null retinoblastoma cells, which is distinct from other types of solid tumors." (PMID 36291051, 2022). "RT-PCR validations further confirmed the expression pattern of E2F2 and HK1 in advanced and non-advanced Rb tumors." (PMID 35626705, 2022).
rheumatoid arthritis (4 papers, 2013 to 2020). A chronic, systemic autoimmune disorder characterized by inflammation in the synovial membranes and articular surfaces. "Since B cells are an important source of HK-1, decreased HK-1 production and release might be an explanation for the efficacy of rituximab, the anti-CD20 monoclonal anibody inducing B cell depletion in rheumatoid arthritis patients." (PMID 23626716, 2013).
thyroid cancer (4 papers, 2016 to 2023). "The series of studies have shown up-regulation of HK1 in several tumors, including colorectal, gastric, and thyroid cancer, and supposed it as an unfavorable prognostic factor." (PMID 28105937, 2016). "The majority of metabolism-related molecules, such as GLUT1 (glucose transporter 1), HK1 (hexokinase 1), LDH-A (lactate dehydrogenase A), GLS1 (glutaminase), and MCT1 (monocarboxylate transporter 1) are upregulated in different subtypes of thyroid carcinoma." (PMID 31947935, 2020). "In order to determine whether leptin and OB3 affect glucose metabolism-related gene expression in human thyroid cancer cells, we measured expression of glucose transporter (GLUT1, GLUT2, GLUT5) genes and the hexokinase 1 gene in a panel of cell lines." (PMID 27050378, 2016).
acute myeloid leukemia (3 papers, 2019 to 2023). Acute myeloid leukemia (AML) is a group of neoplasms arising from precursor cells committed to the myeloid cell-line differentiation. "While HK1 and HK2 are ubiquitously expressed, the less well-studied HK3 is primarily expressed in hematopoietic cells and tissues and is highly upregulated during terminal differentiation of some acute myeloid leukemia (AML) cell line models." (PMID 35538058, 2022).
cardiac hypertrophy (3 papers, 2021 to 2023). "Activation of Akt, which is linked to cardiac hypertrophy in cardiomyocytes, is maintaining a high glucose supply in cancer cells by upregulating Glucose transporter 1(GLUT-1) and hexokinase-1 (HK-1)." (PMID 34899373, 2021). "In addition to HK1, the link between HK2 and cardiac hypertrophy is equally important." (PMID 37938421, 2023).
depression (3 papers, 2022 to 2023). "Autopsy studies have found that the mitochondrial separation of hexokinase 1 in the cerebral parietal cortex tissue of patients with depression is significantly increased, leading to brain tissue cell swelling and toxicity." (PMID 37152596, 2023). "Higher baseline anxiety and depression-like behaviors were detected in male but not in female HK-1-deficient mice, highlighting the importance of investigating both sexes in preclinical studies." (PMID 37973885, 2023). "Higher baseline anxiety and depression-like behaviors were detected in male but not in female HK-1-deficient mice, while other parameter (e.g. body elongation increase) altered by stress was present in both male and female HK-1 deficient animals." (PMID 37973885, 2023). "Therefore, we proposed that GAA and PYGM might affect the occurrence and development of depression by regulating glycogen metabolism in the brain, while HK1 affects the survival and growth of neurons by regulating glycolysis, and eventually affects the mood of depressed patients." (PMID 35990602, 2022).
Hepatic steatosis (3 papers, 2023 to 2025). Steatosis is a term used to denote lipid accumulation within hepatocytes. "The interactions between saroglitazar and ferulic acid with different enzymes and metabolites involved in metabolic dysfunction-associated fatty liver disease (MASLD), such as SORD, HK1, HK2, MgATP, KHK, HK3, ALDOB, ALDOC, and fructose-1-phosphate (F1P)." (PMID 40130107, 2025). "In addition, we observed that the MCD/HK1 group had more severe pathological changes in hepatic steatosis and inflammation compared to the MCD group, and there was a noticeable occurrence of cellular phagocytosis in the MCD/HK1 group of 8-week model." (PMID 37270557, 2023). "Moreover, the interaction betweenlncRP11-675F6.3 and HK1 may provide a new approach for fatty liver treatment." (PMID 37222534, 2023).
influenza (3 papers, 2018 to 2024). An acute viral infection of the respiratory tract, occurring in isolated cases, in epidemics, or in pandemics; it is caused by serologically different strains of viruses (influenzaviruses) designated A, B, and C, has a 3-day incubation period, and usually lasts for 3 to 10 days. "Hemokinin-1 (HK-1) as a molecular adjuvant can enhance circulating antibody responses when co injected with H9N2 whole inactivated influenza vaccine 16,23." (PMID 30555652, 2018). "According to comparative analysis, it was found that H9N2 antigen plus HK-1 encapsulated into chitosan nanoparticles showed significant higher levels of influenza specific antibodies." (PMID 30555652, 2018). "The potential of HK-1 and chitosan nanoparticles was evaluated regarding whether they can enhance specific antibody production in response to H9N2 influenza vaccination." (PMID 30555652, 2018). "In this study, the efficacy of chitosan nanoparticle-based H9N2 influenza vaccine with and without hemokinin-1 (HK-1) as a molecular adjuvant to induce protective immunity against the virus was examined." (PMID 30555652, 2018).
multiple myeloma (3 papers, 2014 to 2023). "Although not specific for SIRT1, HDAC inhibitors were found to down-regulate GLUT1 expression and to inhibit hexokinase 1 enzymatic activity in multiple myeloma cells, underscoring that acetylation plays a key role in regulation of glycolytic metabolism." (PMID 27494892, 2016). "This increase in HK1 might suggest a potential compensatory effect on propranolol‐mediated metabolic inhibition in multiple myeloma cells." (PMID 36245401, 2023).
myocardial infarction (3 papers, 2023 to 2024). Gross necrosis of the myocardium, as a result of interruption of the blood supply to the area, as in coronary thrombosis. "It is known that glycolysis is involved in MF after myocardial infarction and NLRP3 inflammasome is activated by glycolytic inflammation, and HK1 is the first step of glycolysis." (PMID 38268894, 2023).
neuroendocrine tumors (3 papers, 2013 to 2024). "Using real-time PCR, gene expression of GLUT1, HK1 and HK2 were studied in 34 neuroendocrine tumors (NETs) in comparison with 14 colorectal adenocarcinomas (CRAs)." (PMID 26824929, 2013).
renal cell carcinoma (3 papers, 2019 to 2023). "Predominantly, HK has two isoforms HK1 and HK2; the former is widely expressed in adult normal tissues, and the latter is overexpressed in a variety of cancers including renal cell carcinoma." (PMID 35265223, 2022).
retinal degeneration (3 papers, 2023 to 2025). Degeneration of the retina. "In SRP1400-II:1, the RP-like retinal degeneration and neurodevelopmental disorder appears to be primarily related to the presence of a de novo HK1 variant, which is associated with autosomal dominant syndromal RP." (PMID 40269797, 2025). "In SRP1400-II:1, a de novo HK1 variant caused retinitis pigmentosa (RP)-like retinal degeneration and intellectual disability and in USHI105-II:1, MYO7A variants primarily resulted in an Usher syndrome 1 phenotype." (PMID 40269797, 2025). "Compared to other models of retinal degeneration (e.g., rd1, rd10), the PR degeneration in dcKO animals is slower, suggesting that HK1 and PKM1 can partially compensate for the loss of HK2 and PKM2." (PMID 37626853, 2023).
retinitis pigmentosa (3 papers, 2021 to 2025). Retinitis pigmentosa (RP) is an inherited retinal dystrophy leading to progressive loss of the photoreceptors and retinal pigment epithelium and resulting in blindness usually after several decades. "The affected 11-year-old boy with the HK1 mutation did not manifest symptoms of retinitis pigmentosa until his age of examination." (PMID 34193129, 2021).
schizophrenia (3 papers, 2015 to 2025). A major psychotic disorder characterized by abnormalities in the perception or expression of reality. "One study showed a decrease in HK1 attachment to mitochondria in post mortem parietal cortex brain tissue of individuals with schizophrenia which is thought to result in uncoupling of glycolysis with oxidative phosphorylation and, therefore, reduced adenosine triphosphate (ATP) generation." (PMID 26029051, 2015).
Stroke (3 papers, 2018 to 2025). Sudden impairment of blood flow to a part of the brain due to occlusion or rupture of an artery to the brain. "2DG is not a feasible therapeutic after stroke because the resulting suppression of HK1 activity in neurons and other cell types could exacerbate energy compromise in damaged or marginally perfused tissue." (PMID 41152941, 2025).
autism (2 papers, 2024 to 2025). Persistent deficits in social interaction and communication and interaction as well as a markedly restricted repertoire of activity and interest as well as repetitive patterns of behavior. "A potential involvement of VDAC-1 is also proposed for patients with autism where antibodies against the hexokinase-1 (HK-1) have been found." (PMID 38474278, 2024). "Furthermore, level of hexokinase 1 (HK1), which participates in glycolysis and catalyzes the first rate limiting step in glycolysis via phosphorylation of glucose to glucose-6-phosphate was significantly downregulated in adults with autism." (PMID 40779003, 2025).
brain injuries (2 papers, 2018 to 2026). "Similarly, HK1 catalyzes glucose phosphorylation, regulates glycolysis, and is associated with ischemic brain injury." (PMID 41517237, 2026).
cystic kidneys (2 papers, 2016 to 2024). "Using microarray analysis and qPCR, we found an upregulation of genes involved in glycolysis (Hk1, Hk2, Ldha) and a downregulation of genes involved in gluconeogenesis (G6pc, Lbp1) in cystic kidneys of Cy/+ rats compared with wild-type (+/+) rats." (PMID 26752072, 2016). "In addition, enzymes for irreversible steps of glycolysis were upregulated in renal cysts, including hexokinase 1 and 2 (HK1, 1.7×; HK2, 6.2×), and pyruvate kinase (PKM, 1.6×)." (PMID 39000280, 2024).
diabetic retinopathy (2 papers, 2006 to 2013). "We observed only one SNP, rs16926246 at the HK1 locus, which showed nominal significant association with moderate/severe diabetic retinopathy (P value = 3.88 x 10-2, OR = 0.54) when all subjects with and without T2D were combined." (PMID 24244560, 2013).
gastric adenocarcinoma (2 papers, 2020 to 2024). "Normal mucosa (NM) and primary tumor (PT) of 40 metastatic gastric adenocarcinomas patients who received second-line paclitaxel-ramucirumab (PR) were analyzed for mRNA expression of the following genes: HK-1, HK-2, PKM-2, LDH-A, and GLUT-1." (PMID 32372141, 2020).
head and neck carcinoma (2 papers, 2014 to 2021). A carcinoma that arises from the head and neck region. "MiR-143 and miR-138 down-regulated glycolytic enzymes, hexokinase 2 (HK2) and HK1, respectively, in head and neck carcinoma." (PMID 25541689, 2014).
Infertility (2 papers, 2019 to 2021). "HK1 is found to be associated with active spermatogenesis in mice, and might abrogate the process of spermatogenesis leading to infertility." (PMID 31288842, 2019).
lymph node metastasis (2 papers, 2015). "High HK1 expression was significantly associated with lymph node metastasis (P < 0.001) and stage III and IV disease (P = 0.006)." (PMID 26576639, 2015).